MYCN (MYCN proto-oncogene, bHLH transcription factor)
Diseases named in the same sentence as MYCN in open-access papers (continued):
Sharing a sentence is not in itself a finding about the gene and the disease.
neuroblastoma (continued). "Combined PB and RA treatment significantly reduced proliferation and, importantly, was also effective at further promoting neuroblastoma differentiation in both MYCN-amplified and non-MYCN-amplified neuroblastoma cell lines." (PMID 37734383, 2023). "Collectively, these results indicated the therapeutic implications of LIG4 inhibition in combination with DNA-PKi for MYCN-amplified neuroblastomas." (PMID 37240360, 2023). "BTYNB decreased neuroblastoma cell viability, as previously reported, disturbed MYCN mRNA association with IGF2BP1 and impaired MYCN at only modest reduction of IGF2BP1." (PMID 37246217, 2023). "In sum, this suggested that IGF2BP1 is a potent, druggable oncogene in neuroblastoma synergizing with MYCN in a transcriptional/post-transcriptional feedforward loop resulting in the upregulation of oncogenes like the 17q-located BIRC5." (PMID 37246217, 2023). "Age at diagnosis, MYCN amplification and neuroblastoma stage are critical biomarkers of neuroblastoma." (PMID 37904225, 2023). "Inhibition of MYCN genes as previously discussed also holds potential in cases of pediatric Neuroblastoma." (PMID 37314524, 2023). "ALYREF-mediated upregulation of USP3 expression prevented MYCN protein degradation and resulted in increased neuroblastoma cell viability in vitro and in vivo." (PMID 37170124, 2023). "BET bromodomain inhibitors like JQ1 and I-BET726 displace BRD4 from the MYCN promoter, leading to improved survival in various in vivo neuroblastoma models by inhibiting tumor growth and MYCN downregulation." (PMID 38087370, 2023). "The penetrance of neuroblastoma in Th-MYCN+/− FCM mice matches that observed in our parental Th-MYCN colony, and is comparable to that previously reported for MYCN transgene hemizygotes on the 129X1 background." (PMID 37569447, 2023). "The initiation and development of neuroblastoma are underpinned by crucial genetic factors, including but not limited to MYCN amplifications, MDM2 amplifications or overexpression, ALK mutations or amplifications, and segmental chromosomal abnormalities." (PMID 37834394, 2023). "The retinoid 13-cis-RA (13-cis-RA, isotretinoin), an isomer of ATRA, is a cancer chemoprevention drug that causes differentiation, decreased proliferation and inhibition of MYCN expression in progressive neuroblastoma cells." (PMID 38249515, 2023). "The engagement of MYCN in neuroblastoma metabolic rewiring was further underscored by the finding of its positive feedback loop with enzyme aldehyde dehydrogenase family 18 member A1 (ALDH18A1), a critical component in glutamine metabolism." (PMID 37835497, 2023). "The identification of LRP8 as a specific vulnerability of MYCN‐amplified neuroblastoma cells was confirmed in constitutive and inducible LRP8 knockout orthotopic xenografts." (PMID 37435859, 2023). "The data above support the requirement of LRP8 for the establishment and maintenance of MYCN‐amplified SK‐N‐DZ neuroblastoma by preventing ferroptosis." (PMID 37435859, 2023). "Further, we attempted to determine the accuracy of ZNF436 in the prediction of 1p deletion, MYCN amplification and in the prediction of the overall survival of neuroblastoma." (PMID 37904225, 2023). "In human neuroblastomas, NCYM is always co-amplified with MYCN, and its expression level is associated with poor prognosis." (PMID 38074684, 2023). "The neuroblastoma MYC oncogene MYCN recruited HDAC2 to miR-183 promoter sequences to decrease the expression of miR-183 in neuroblastoma cells." (PMID 36968022, 2023). "Activity of the wt reporter was consistently reduced in comparison to control and mut reporters, confirming conserved miRNA-dependent regulation of the MYCN 3’UTR in neuroblastoma cell models." (PMID 37246217, 2023). "Combinations of ZNF436 expression with MYCN amplification or age of diagnosis achieved better prognosis of neuroblastoma." (PMID 37904225, 2023).
neuroblastoma (continued). "In MYCN-driven neuroblastoma cells, upregulation of the multidrug transporters ABCB1 and ABCG2 results in resistance to THZ1117." (PMID 36720920, 2023). "Amplification of the MYCN oncogene and inactivation of the ATRX tumor-suppressor gene are associated with high-risk disease and poor prognosis in neuroblastoma." (PMID 37190157, 2023). "For neuroblastoma, MYCN amplification, 1q gain as well as 1p and 11q deletions were independent predictors of decreased overall survival." (PMID 37189699, 2023). "Our previous results suggested that ZNF436 was associated with the overall survival of neuroblastoma and showed the synergistic prognostic effects of ZNF436 with MYCN amplification or age of diagnosis in neuroblastoma." (PMID 37904225, 2023). "The same results were observed for the following subgroup analyses: by age group, tumour stage and MYCN status for neuroblastoma; with stratification by gender for medulloblastoma; by considering laterality for retinoblastoma." (PMID 36726302, 2023). "To model tumors with low mutational burden, we employed oncogene-driven cell lines that were derived from spontaneous tumors in transgenic mice, namely the Ret melanoma cell line and the MYCN-amplified neuroblastoma cell line 9464D." (PMID 36757800, 2023). "We observed that MYCN-driven neuroblastoma spheroids were relatively sensitive to DNA-Pki, which was consistent with the previous finding that L-MYC has synthetic lethal interactions with DNA-PKcs." (PMID 37240360, 2023). "MYCN mRNA expression has been found to increase with later stages of neuroblastoma in patient samples, while RUNX3 expression, comparatively, shows a decrease." (PMID 36899853, 2023). "In recent years, it has been established that MYCN is an important regulator of several miRNAs in the formation of neuroblastoma." (PMID 37592273, 2023). "In neuroblastoma cells, tryptanthrin is shown to inhibit MYCN expression and thereby potentiate cell killing." (PMID 38249515, 2023). "While metabolism of neuroblastoma tends to display hallmarks of the glycolytic “Warburg effect,” aggressive, in particular MYCN-amplified tumours, retain functional mitochondrial metabolism, allowing for survival and proliferation under nutrient stress." (PMID 37414143, 2023). "Investigating these thoroughly, I define here, the ‘Metastatic wheel of neuroblastoma’ driven by MYCN oncogene." (PMID 37274289, 2023). "This analysis strengthens our findings, since it illuminates that several of the upregulated metabolism-related TFs described in our computational study are targeted by an additional TF that is critical for neuroblastoma and is also an MYCN target." (PMID 37835497, 2023). "To investigate the effect of MYCN on mitotic dysregulation and its functional consequences in neuroblastoma cells, we performed siRNA knockdown of AURKB, BUB1, and KIFC1 in MYCN-regulable SHEP21N cells." (PMID 37958555, 2023). "Another dietary antioxidant compound, isoliquiritigenin (ISLQ), is a chalcone-type flavonoid that has been shown to increase cellular ROS and exert cytotoxic effects on MYCN-amplified neuroblastoma cells." (PMID 38249515, 2023). "After dividing the circ_0000285 high and low expression groups based on the mean circ_0000285 expression, circ_0000285 with high expression suggested a higher International Neuroblastoma Staging System stage (P = 0.0430) and MYCN amplification (P = 0.0361)." (PMID 37465351, 2023). "Serum MYCN mRNA level in the neuroblastoma group was significantly higher than that in the control group (P < 0.05)." (PMID 37592273, 2023). "On this basis, we summarized recent studies on the reversal strategies to overcome therapy resistance of neuroblastoma such as targeting ATP-binding cassette transporters, MYCN gene, cancer stem cells, hypoxia, and autophagy." (PMID 36874032, 2023). "In neuroblastoma, MYCN maintains stability via binding to Aurora kinase A (AURKA), which inhibits association of Fbw7 to ubiquitinate MYCN." (PMID 36899853, 2023).
neuroblastoma (continued). "In two patients, liquid biopsies were used for prognostication, by MYCN ddPCR in a patient with neuroblastoma and by RT-qPCR testing rhabdomyosarcoma-specific mRNA in bone marrow of a patient with a rhabdomyosarcoma (case 4 and 5)." (PMID 37664065, 2023). "To explore the therapeutic potential of targeting mitotic dysregulation, we showed that genetic and chemical inhibition of mitosis led to selective cell death in neuroblastoma cell lines with MYCN over-expression." (PMID 37958555, 2023). "Next, using both zebrafish and mammalian model systems, they show that reduced expression of the GAS7 promotes metastasis of MYCN-amplified neuroblastoma cells." (PMID 37274289, 2023). "These additional models recapitulated the observation that LRP8 is essential to support the viability of human neuroblastoma cell lines and that it is also crucial in a cell line derived from a MYCN‐driven genetic neuroblastoma model." (PMID 37435859, 2023). "Neuroblastoma (NB), a childhood cancer arising from the neural crest, poses significant clinical challenges, particularly in cases featuring amplification of the MYCN oncogene." (PMID 38069407, 2023). "So, in this study, using independent risk factors age of diagnosis, MYCN amplification and ZNF436, we developed a nomogram model to predict the overall survival of neuroblastoma." (PMID 37904225, 2023). "For example, in neuroblastoma, this would be coupled to the Aurora-A/MYCN modulation of DNA synthesis in S-phase." (PMID 37414143, 2023). "MYCN can also drive transcription of ATF4 in neuroblastoma cells, and it was demostrated that targeting either MYCN or ATF4 leads to decreased expression levels of PHGDH, PSAT1, SHMT2, MTHFD2, and MTHFD1L." (PMID 37949226, 2023). "The significance and mechanism of polyamine metabolism in neuroblastoma and the role of MYCN in polyamine-regulated neuroblastoma progression have been reviewed in detail elsewhere." (PMID 38249515, 2023). "In this work, we emphasize a well-known cancerous genomic alteration: the amplification of MYCN and its downstream effects in neuroblastoma phenotype evolution." (PMID 37835497, 2023). "The role(s) of MYCN in metabolic reprogramming-related gene expression program evolution in neuroblastoma has remained largely elusive." (PMID 37835497, 2023). "Herein, we computationally investigated the gene expression characteristics that distinguish neuroblastoma-MYCN-amplified from neuroblastoma non-MYCN-amplified cancer cells, and we addressed the upregulation of several metabolism-related TF-encoding genes." (PMID 37835497, 2023). "In ADC histogram analysis of neuroblastomas, MYCN-amplified neuroblastomas had statistically significant higher maximum ADCs and lower minimum ADCs." (PMID 37762918, 2023). "MYCN amplification is characteristic of neuroblastoma and induces malignant processes leading to neuroblast formation." (PMID 37685987, 2023). "Identifying the vulnerability of altered DNA repair machinery that displays synthetic lethality with MYCN amplification is a therapeutic rationale in unfavourable neuroblastoma." (PMID 37240360, 2023). "Collectively, deficiency of both RUNX3 and p73 caused by deletion of the 1p36 region is likely to provide a favorable environment for MYCN-driven neuroblastomas." (PMID 36831211, 2023). "The MYCN gene is a transcription factor that is amplified in human neuroblastoma and is related to the patient’s prognosis." (PMID 38004392, 2023). "In this review, we focus particularly on lipid metabolism in embryonal tumors with deregulated MYCN function, specifically neuroblastoma, retinoblastoma, Wilms tumor, medulloblastoma, and rhabdomyosarcoma." (PMID 37046804, 2023). "We therefore analyzed gene expression in MYCN-induced neuroblastomas in GATA/GATA, TATA/TATA and lmo1–/– genetic backgrounds by RNA-Seq." (PMID 37183825, 2023). "Tumors seem to mirror this pattern of expression, as MYCN is overexpressed in several neural tumors including neuroblastomas." (PMID 36987269, 2023).
neuroblastoma (continued). "The levels of LDH, NSE, CEA, and MYCN in the neuroblastoma group were clearly higher than those in the control group (P < 0.05)." (PMID 37592273, 2023). "The induction of MYCN expression in SHEP MYCN-ER neuroblastoma cells, which carry a single copy of the MYCN gene, led to a time-dependent activation of GLS2 but not GLS." (PMID 38067269, 2023). "DNA-PKi exhibited an inhibitory effect on the proliferation of MYCN-driven neuroblastoma spheroids, whereas variable sensitivity was observed in those cell lines." (PMID 37240360, 2023). "We have also shown that the expression of the CCDC86 gene is regulated by MYCN and has prognostic value in neuroblastoma." (PMID 36695333, 2023). "The results showed that the detection of serum MYCN mRNA level can effectively diagnose neuroblastoma." (PMID 37592273, 2023). "Isotretinoin-mediated neuroblastoma cell differentiation is orchestrated by targeting MYCN, cyclin D3, and Wnt10B." (PMID 38249515, 2023). "MYCN has been amply described in central nervous system malignancies like neuroblastoma and ependymoma." (PMID 38132443, 2023). "They observed that overexpressing LMO1 alone do not develop neuroblastoma but its overexpression along with increased MYCN expression led to enhanced neuroblastoma initiation and disease penetrance." (PMID 37274289, 2023). "The N-cym protein regulates the stability of the proto-oncogene MYCN in neuroblastoma cells, while the SPANX family proteins are expressed in human spermatozoa and are extensively studied in Down syndrome patients." (PMID 37879070, 2023). "Two interesting findings from this study are the possibility of ceRNA induced by MYCN which acts like a Let-7 miRNA sponge and the role of chromosomal deletions in neuroblastoma." (PMID 37206500, 2023). "At the same time, a large number of research data show that the abnormal amplification and high-level expression of the MYCN gene are positively correlated with the malignant progression, poor prognosis, and mortality of neuroblastoma." (PMID 36770809, 2023). "MYCN-amplification correlates with neuroblastoma metastasis, by contributing to a number of processes implicated in cell migration and invasion." (PMID 37414143, 2023). "ZNF436 was down-regulated in MYCN amplified neuroblastoma patients in E-MTAB-1781, GSE13136, GSE73517, TARGET, GSE16476, GSE62564 and GSE85047 datasets." (PMID 37904225, 2023). "ZNF436 was down-regulated in 1p deleted neuroblastoma and ZNF436 was lower in neuroblastoma patients with MYCN amplification or age at diagnosis ≥ 18months, or with stage 4 neuroblastoma." (PMID 37904225, 2023). "Another study found that exosome derived from natural killer (NK) cells carrying the tumor suppressor miR-186 was cytotoxic to MYCN-amplified neuroblastoma cell lines." (PMID 37426487, 2023). "In neuroblastoma, chromosomal gains at chromosome 17q, including IGF2BP1, and MYCN amplification at chromosome 2p are associated with adverse outcome." (PMID 37246217, 2023). "We found that MYC and MYCL were enriched in high-NE-score SCLC lines, whereas MYCN amplification was enriched in high-NE-score neuroblastoma lines." (PMID 37255415, 2023). "About half of the neuroblastomas were metastatic (47.4%); 19.6% of the cases with known MYCN status (1915 cases) were MYCN amplified." (PMID 36726302, 2023). "Beierle and colleagues observed upregulation of FAK in MYCN-amplified and overexpressed neuroblastoma cell lines and in the advanced-stage human neuroblastoma tumor specimens." (PMID 37274289, 2023). "Other Lim-only protein family members generally don’t compensate for diminished lmo1 expression in zebrafish MYCN-driven neuroblastomas." (PMID 37183825, 2023).
neuroblastoma (continued). "MYCN-amplified neuroblastoma often presents as a highly aggressive metastatic disease with a poor prognosis." (PMID 38014922, 2023). "That is, these patients with neuroblastoma had the transcriptional fingerprint of activated MYCN yet would have been misclassified by conventional cytogenetics." (PMID 36932241, 2023). "To investigate how MYCN amplification mechanistically imposes the metabolic rewiring of neuroblastoma cells, we first attended to the in cis distribution of its encoded product." (PMID 37835497, 2023). "In Th-MYCN mice, human MYCN expression is driven by a rat tyrosine hydroxylase (Th) promoter resulting in the development of neuroblastomas originating predominantly from abdominal ganglion structures." (PMID 36449545, 2022). "There had been several established prognostic factors in neuroblastoma, including age, INSS stage, MYCN status, and the clinical risk classification system." (PMID 36605200, 2022). "Age of diagnosis and MYCN amplification were independent prognostic factors of pediatric neuroblastoma in GSE85047 and E-MTAB-1781 datasets." (PMID 35764946, 2022). "Combinations of E2F1, E2F3 with MYCN amplification or age of diagnosis achieved better prognosis of neuroblastoma." (PMID 35764946, 2022). "Beyond neuroblastoma, MYCN amplification has also been found in different neoplasias, and the list of malignancies where it plays a role is expanding." (PMID 35490242, 2022). "This study delineates that SMAD9 forms a positive transcriptional feedback loop with MYCN and represents a unique tumor-dependency for MYCN-amplified neuroblastoma." (PMID 36539767, 2022). "Subsequent investigation revealed that MYCN-amplified neuroblastoma cells express high levels of ASCT2 (also known as SLC1A5), which functions as a major transporter for uptake of glutamine in MYCN-amplified neuroblastoma cells." (PMID 36077650, 2022). "The functional significance of the MYCN-driven glutamine synthesis in neuroblastoma cells remains to be determined." (PMID 36077650, 2022). "In neuroblastoma, the MYCN gene can be amplified with the help of ecDNA, which increased the expression of this gene and then upregulated the expression of multidrug resistance genes, resulting in enhanced resistance." (PMID 36793345, 2022). "We also verified that the MYCN mRNA inhibition translated to a decrease in proteins and that BGA002-RA treatment led to a stronger N-Myc decrease in three MYCN-amplified neuroblastoma (MNA-NB) cell lines." (PMID 35490242, 2022). "MYCN gene amplification, the strongest prognostic marker of aggressive neuroblastoma, is detected on invasive biopsy tissues." (PMID 35681607, 2022). "MYCN amplification, found in approximately 20% of neuroblastoma patients, indicates particularly bad prognosis." (PMID 34522028, 2022). "We retrieved RNA-seq datasets from two distinct classes of neuroblastoma cell lines, which differ in MYCN amplification, and we performed an intratumor transcriptomics analysis." (PMID 36139535, 2022). "This inverse relationship between α1 integrin and MYCN confirms that it is a favorable CAM in neuroblastoma." (PMID 35574403, 2022). "Inhibitors of Cyclin-dependent kinases 7: The active involvement of super-enhancers of the over-driven MYCN expression in MYCN-amplified neuroblastoma came to light through the study of a covalent CDK7 inhibitor, THZ1." (PMID 35053227, 2022). "Since β1 integrin was overexpressed in MYCN amplified cells, using FNIII14 in vivo resulted in inhibited neuroblastoma tumor growth and consequently less MYCN amplification in the tumor cells." (PMID 35574403, 2022).